RN7SL366P (RNA, 7SL, cytoplasmic 366, pseudogene)
Gene: Miscellaneous RNA gene on chromosome 6 (163,840,561 to 163,840,852, forward strand). Ensembl gene ENSG00000266128.
Homologues: Orthologues: chimpanzee Metazoa_SRP (98% identical), macaque Metazoa_SRP (88% identical). Paralogues in human: RN7SL1 (83% identical), RN7SL2 (82% identical), RN7SL679P (81% identical), RN7SL3 (81% identical), RN7SL14P (80% identical), RN7SL296P (80% identical), RN7SL220P (80% identical), RN7SL672P (80% identical), RN7SL714P (79% identical), RN7SL566P (79% identical), RN7SL664P (79% identical), Metazoa_SRP (79% identical), and 702 more.